TRAV18 (T cell receptor alpha variable 18)
Description:
V region of the variable domain of T cell receptor (TR) alpha chain that participates in the antigen recognition. Alpha-beta T cell receptors are antigen specific receptors which are essential to the immune response and are present on the cell surface of T lymphocytes. Recognize peptide-major histocompatibility (MH) (pMH) complexes that are displayed by antigen presenting cells (APC), a prerequisite for efficient T cell adaptive immunity against pathogens. Binding of alpha-beta TR to pMH complex initiates TR-CD3 clustering on the cell surface and intracellular activation of LCK that phosphorylates the ITAM motifs of CD3G, CD3D, CD3E and CD247 enabling the recruitment of ZAP70. In turn ZAP70 phosphorylates LAT, which recruits numerous signaling molecules to form the LAT signalosome. The LAT signalosome propagates signal branching to three major signaling pathways, the calcium, the mitogen-activated protein kinase (MAPK) kinase and the nuclear factor NF-kappa-B (NF-kB) pathways, leading to the mobilization of transcription factors that are critical for gene expression and essential for T cell growth and differentiation. The T cell repertoire is generated in the thymus, by V-(D)-J rearrangement. This repertoire is then shaped by intrathymic selection events to generate a peripheral T cell pool of self-MH restricted, non-autoaggressive T cells. Post-thymic interaction of alpha-beta TR with the pMH complexes shapes TR structural and functional avidity.
Synonyms: TCRAV18S1
Gene: T-cell receptor variable (V) gene on chromosome 14 (22,003,106 to 22,003,673, forward strand). Ensembl gene ENSG00000211798.
Subcellular location: Cell membrane
Gene Ontology:
Biological process: adaptive immune response
Cellular component: immunoglobulin complex; plasma membrane
Homologues: Orthologues: mouse Trav12-2 (63% identical), mouse Trav12d-3 (63% identical), mouse Trav12n-3 (63% identical), mouse Trav12-3 (62% identical), mouse Trav12d-2 (62% identical), mouse Trav12n-2 (62% identical), mouse Trav12d-1 (61% identical), mouse Trav12n-1 (61% identical), mouse Trav12-1 (59% identical). Paralogues in human: TRAV9-2 (52% identical), TRAV9-1 (46% identical), TRAV40 (41% identical), IGKV1-12 (31% identical), IGKV1D-12 (31% identical), TRDV1 (30% identical), IGKV1-27 (29% identical), IGKV1-39 (29% identical), IGKV1-5 (29% identical), IGKV1D-16 (29% identical), IGKV1D-39 (29% identical), IGKV1OR2-108 (29% identical), and 81 more.